CCND1 (cyclin D1)
Diseases named in the same sentence as CCND1 in open-access papers (continued):
Sharing a sentence is not in itself a finding about the gene and the disease.
gastric cancer (continued). "Moreover, ZIC1 inhibits cell cycle regulatory kinases, p21, p27 and cyclin D1, thus leading to G1/S cell cycle transit in gastric cancer cells." (PMID 22799764, 2012). "In conclusion, down-regulation of miR-27a might inhibit proliferation and drug resistance of gastric cancer cells through regulation of P-gp, cyclin D1 and p21." (PMID 21569481, 2011). "In the gastric cancers examined, 27 of 190 cases (14.2%) showed overexpressed Cyclin D1." (PMID 20525401, 2010). "The degree of cyclin D1 overexpression has been correlated with invasive stages of gastric cancer." (PMID 16552434, 2006). "In addition, we found that PAR-1, the PI3K/Akt pathway, and cyclin D1 may be potential downstream targets of ncRuPAR-mediated regulation of human gastric cancer cell proliferation and apoptosis." (PMID 36438913, 2022). "In addition, we checked signalling molecules downstream of β-catenin and found that TCF-4, c-Myc and Cyclin D1 were reduced in Mist1-overexpressing cells, which indicates that the Wnt/β-catenin signalling pathway was inhibited in Mist1-overexpressing gastric cancer cells." (PMID 34149921, 2021). "In addition, CCND1 is an important target for cell proliferation in gastric cancer, and it has been shown that high CCND1 expression levels are closely related to shorter survival rates of gastric cancer patients." (PMID 34899944, 2021). "The possible mechanisms of the components of the Zhishi-Baizhu herb pair in treating gastric cancer might be related to luteolin and naringenin, which intervened with the targets AKT1, MMP9, IL-6, CCND1, BCL2, MTOR, and MDM2, and are linked with the PI3K-Akt and IL-17 signaling pathways." (PMID 34899944, 2021). "Teng and colleagues demonstrated that the expression of miR-107 could be suppressed by Lin28, a highly conserved RNA-binding protein, and resulting in up-regulation of C-myc and P-gp and down-regulation of cyclin D1, and subsequently leading to chemo-resistance in gastric cancer cells." (PMID 32883962, 2020). "Similarly, sweroside and lanatoside C could arrest leukemia cells or gastric cancer cells at G2/M while lowering the expression of cyclin D1." (PMID 31767027, 2019). "Therefore, the promoting role of CORO1C in both proliferation and metastasis of gastric cancer cells might be mediated by cyclin D1 and vimentin." (PMID 30974047, 2019). "For example, lncRNA urothelial cancer associated 1 (UCA1) is upregulated in gastric cancer tissues, and promotes the growth and cell cycle process through binding to enhancer of zeste 2 polycomb repressive complex 2 subunit (EZH2) and facilitating cyclin D1 expression in gastric cancer cells." (PMID 29773901, 2018). "Therefore, SAHA might transcriptionally up-regulate the expression of p21 and p27 at both protein and mRNA level to cause G1 arrest of gastric cancer cells, which SAHA- induced Cyclin D1 hypoexpression was also responsible for." (PMID 27447743, 2016). "Moreover, JNK activation in gastric cancer was positively correlated with the proliferation index (evaluated by Ki-67 labeling) and cell cycle-regulatory molecules such as cyclin D1 (P = 0.045) and cyclin E (P < 0.001), which are present more frequently in early-stage gastric carcinomas." (PMID 27268017, 2016). "Amplification of CCND1 may have potential clinical impact in gastric cancer for two reasons." (PMID 25649416, 2015). "First, CCND1 amplification has been linked to resistance to the EGFR inhibitor gefitinib in experimental models of head & neck cancer, raising the possibility that it might also negatively impact the efficacy of potential anti-EGFR therapy in gastric cancer." (PMID 25649416, 2015). "Since overexpressed cyclin D1 is closely related to human gastric cancer progression, inhibition of cyclin D1 using specific targeting could be an effective treatment method of human gastric cancer." (PMID 24618206, 2014).
gastric cancer (continued). "Importantly, the current study reported the inverse correlation between miR-9 levels and the expression of cyclin D1 and Ets1 in gastric cancer tissues, implying that cyclin D1 and Ets1 may be negatively regulated by miR-9." (PMID 23383271, 2013). "Thus, our findings suggest that cyclin D1 expression in gastric cancer cells might be regulated by signaling molecules such as Ras, Nuclear factor-κB or β-catenin rather than GSK-3β as previously reported." (PMID 20704706, 2010). "However, in GC, investigations have primarily focused on surface phenomena such as Cyclin D1, AKT, and the Wnt/β-catenin signaling pathway, while deeper mechanistic insights into TRIM24’s role in gastric cancer remain inadequately explored." (PMID 41430038, 2025). "Dihydroartemisin downregulated PCNA and MMP-2, mediated by p16-Cyclin D1/CDK4-Rb pathway, suppresses the cell growth and metastasis of human gastric cancer (GC) cells." (PMID 39161904, 2024). "Gentiopicroside affects the expression of CCNE1, p-P38, CCND1, and p-AKT at the protein level, thereby exerting its anti-gastric cancer effect." (PMID 39086391, 2024). "Knockdown of TRIM29 in the gastric cancer cell line MGC803 decreased the expression levels of β-catenin, cyclin D1, and c-Myc, indicating that TRIM29 plays a role as an oncogene in gastric cancer." (PMID 38213743, 2024). "SETDB1 mediates the malignant biological behaviour of gastric cancer by interacting with ERG and enhancing the promoter activity of CCND1 and MMP9." (PMID 38317200, 2024). "ESRRG has been identified as a candidate tumor suppressor gene in gastric cancer that can inhibit Wnt signaling via the suppression of transcription factor 4 (TCF4)/lymphoid enhancer-binding factor 1 (LEF1), binding to the Cyclin D1 (CCND1) promoter." (PMID 37240447, 2023). "In gastric cancer cells, CORO1C expression facilitated cancer cell aggressiveness (e.g., cell viability, colony formation, and metastasis) by positively regulating cyclin D1 and vimentin expression." (PMID 37239355, 2023). "A long non-coding RNA, GHET1, is upregulated in gastric cancer, and its inhibition in gastric cancer cells leads to reductions in CDK2, Cyclin E1, CDK6, CDK4, and Cyclin D1." (PMID 36769170, 2023). "Another oncogene named Sine oculis homeobox homolog 1 (SIX1) is involved in positively regulating the expression of Cyclin D1 along with epithelial–mesenchymal transition (EMT)-related proteins and p-ERK and MMP2 in gastric cancer cells." (PMID 36769170, 2023). "Advanced gastric cancer (GC) is a lethal malignancy, harboring recurrent alterations in cell cycle pathway, especially the CDKN2A-CDK4/CDK6/CCND1 axis." (PMID 36755269, 2023). "In another study, involving gastric cancer cell line SGC-7901, curcumin treatment led to the stabilization of miR-34a, which in turn inhibited Cyclin D1 and CDK4 from inducing cell cycle arrest and apoptosis." (PMID 36769170, 2023). "The miR-129-5p induces cell cycle arrest in vitro and in vivo conditions in gastric cancer and targets HOXC10 directly for its downregulation, which further functions in regulating the expression of Cyclin D1." (PMID 36769170, 2023). "For example, as a prognostic biomarker for gastric cancer, AURKB promotes the progression of gastric cancer through epigenetic activation of CCND1 expression." (PMID 37318676, 2023). "When we assessed the expression status of individual gastric cancer oncogenes (e.g., CEACAM6, EGFR, MET, CCND1, and KRAS) among the tumor epithelial clusters, the EpiInt1 tumor epithelial cluster exhibited the largest increase." (PMID 34642171, 2022). "In gastric cancer, CD44 regulates stem cell proliferation by increasing cyclin D1 expression, and the expressions of CD44 and cyclin D1 are positively correlated with tumor differentiation." (PMID 36042265, 2022).
gastric cancer (continued). "Ye noted that by downregulating SOX17 expression, the expression levels of cyclin D1 and P27 were upregulated, thereby shortening the cell cycle and promoting the proliferation and invasion of MKN45 gastric cancer cells." (PMID 36072972, 2022). "In gastric cancer, upregulated DDX21 increased cell proliferation in vitro and tumor progression in mice via the Cyclin D1 and CDK2 pathways." (PMID 35371306, 2022). "The prevailing view is that high levels of cyclin D1 expression have a positive correlation with poor prognosis in a wide variety of tumors such as nasopharyngeal carcinoma (NPC), gastric cancer tissues, and squamous cell carcinoma of the head and neck." (PMID 36059670, 2022). "The lncRNA SUMO1P3 enhances proliferation, invasiveness, and drug resistance in gastric cancer cell lines by directly binding to CNBP, resulting in high levels of c-myc and cyclinD1 (CCND1)." (PMID 35991559, 2022). "miR-33a directly targeted cyclin-dependent kinases 6 (CDK6), cell cycle protein D1 (CCND1), and serine/threonine kinase PIM-1, and expression was down-regulated in gastric cancer tissues and cell lines, thereby inhibiting gastric cancer cell proliferation." (PMID 35743814, 2022). "HOTAIR knockdown had antitumor effects by suppressing CCND1 and CCND2 expression by stimulating miRNA‐206 in gastric cancer in vitro study." (PMID 33473276, 2021). "In this study, western blot analysis found that CCNI2 knockdown resulted in reduced AKT phosphorylation level, downregulated CCND1 and CDK1, upregulated MAPK9 expression in gastric cancer cells." (PMID 34895232, 2021). "Additional experiments led researchers to discover that when SHP-1 protein expression was increased, gastric cancer cells exhibited reduced phosphorylation of STAT3, which resulted in downstream inhibition of Cyclin D1 and XIAP." (PMID 34884670, 2021). "Meanwhile, our findings also found that the protein expression of Cyclin D1 and PCNA in metastatic gastric cancer cells were much higher than those in primary gastric cancer cells." (PMID 32139657, 2020). "In gastric cancer, lncRNA UCA1 enhanced the translation of cyclin D1 via recruiting EZH2 and further precipitated the proliferation and cell cycle progression of gastric cancer." (PMID 32587476, 2020). "We successfully established stable BGC823 gastric cancer cell lines with AURKB knockdown and with AURKB knockdown plus CCND1 overexpression." (PMID 31982864, 2020). "To validate their relationship in gastric cancer cells, we used FAK inhibitor to block its function and the effects of Rab11a on cyclin D1, MMP2, and Bcl-2 were significantly reduced." (PMID 33178272, 2020). "This study demonstrates that AURKB promotes gastric tumorigenesis potentially through epigenetically activating CCND1 expression, suggesting AURKB as a promising therapeutic target in gastric cancer." (PMID 31982864, 2020). "In gastric cancer, ASK1 overexpression induces the transcription of cyclin D1 through AP-1 activation, and ASK1 levels are regulated by cyclin D1 in turn via the Rb-E2F (retinoblastoma-E2F transcription factor) pathway." (PMID 32231094, 2020). "Abnormal high expression of CCND1 or CDK4 has been found in various tumors, such as pancreatic cancer, bladder cancer and gastric cancer." (PMID 32742488, 2020). "The result demonstrated that PIN1 significantly promotes the expression of cyclin D1, MMP2, MMP9, β-catenin, and N-cadherin, while inhibits E-cadherin expression in gastric cancer." (PMID 32703934, 2020). "Meanwhile, in HP-CagA+-infected gastric cancer cells, the expression of CDK4 and cyclin D1 was detected when reg3 expression was altered." (PMID 31905669, 2019). "Expression of mediators downstream of RON, including c-Myc, Cyclin D1, c-Jun, survivin and AKT, were also increased in gastric cancer tissues." (PMID 31085796, 2019).
gastric cancer (continued). "Mechanistic investigation suggested that METTL3 led to inactivation of the AKT signaling pathway in human gastric cancer cells, including decreased phosphorylation levels of AKT and expression of down-stream effectors p70S6K and Cyclin D1." (PMID 30886897, 2019). "Cyclin D1 was detected to mediate cellular cycle change and proliferation guided by WDR5 in gastric cancer." (PMID 30974047, 2019). "The results of western blot analyses showed that the expression of cyclin D1 and Bcl2 was downregulated while that of the active forms of caspase-3 ad PARP was upregulated in DANCR knockdown gastric cancer cells." (PMID 29416741, 2018). "Reinforced SHP-1 expression in gastric cancer cells effectively inhibits STAT3 activity and its target genes such as cyclin D1, matrix metalloproteinases-9 (MMP-9), vascular endothelial growth factor-1 (VEGF-1), and survivin." (PMID 29409467, 2018). "Mechanistically, in gastric cancer cells, WDR5 induces histone H3K4 trimethylation at the Cyclin D1 gene promoter and Cyclin D1 gene transcription, leading to cancer cell proliferation." (PMID 30488017, 2018). "In a Chinese study, Nox4 expression was correlated with tumor size and poor prognosis in 90 patients with gastric cancer and knockdown of NOX4 expression blocked cell proliferation and the expression of Cyclin D1, BAX and so on in vitro." (PMID 30513726, 2018). "The results of quantitative RT-PCR analyses showed that the expression of proliferation-related genes including cyclin D1 and Bcl2 was downregulated while that of apoptosis-related gene Bax was upregulated in DANCR knockdown gastric cancer cells." (PMID 29416741, 2018). "In gastric cancer cells, Nrdc has been shown to enhance the ectodomain shedding of TNF-α and subsequent activation of cell cycle-promoting genes, such as Ccnd1 and bcl218." (PMID 29093577, 2017). "Vitamin D3 may act as an antagonist of hedgehog signaling to suppress viability of gastric cancer cells, and it also has a synergistic effect with other anticancer drugs by reducing mRNA expression of the target genes of hedgehog signaling ( Ptch1, Gli1, cyclin D1 and bcl2)." (PMID 28206978, 2017). "Previously, the potential of curcumin in regulating gastric cancer was thought attributable to downregulation of oncogenic pathways, such as PAK1 and cyclin D1 pathways." (PMID 28781948, 2017). "Morusin markedly inhibited gastric cancer cell proliferation by down-regulating CDKs and Cyclins, such as CDK2, CDK4, Cyclin D1 and Cyclin E1." (PMID 28915664, 2017). "Our results suggest that miR-375 can induce G1 cell cycle arrest by inhibiting cyclin D1, cyclin D3, and the phosphorylation of Rb in AGS and MKN-28 gastric cancer cells." (PMID 27689991, 2016). "In cell culture, treatment of gastric cancer cells with a JNK inhibitor, SP600125, decreased cyclin D1 protein expression and colony formation." (PMID 27268017, 2016). "In gastric cancer, ASK1 and cyclin D1 were shown to form a positive feedback loop that promotes tumorigenesis." (PMID 27655673, 2016). "Our results indicated that the overexpression of miR-375 inhibited the expression of cyclin D1 and cyclin D3 and the phosphorylation of Rb in AGS and MKN-28 human gastric cancer cells." (PMID 27689991, 2016). "For this purpose, we selected 4 genes (HER2, CCND1, MYC and EGFR) with established relevance for gastric cancer, which were previously reported to be amplified." (PMID 25649416, 2015). "Markedly, higher rates was only reported from two small studies finding MYC amplification in 3 of 7 gastric cancers by FISH and in 17 of 33 tumors using less quantitative PCR for CCND1 amplification analysis." (PMID 25649416, 2015). "MiR-9 suppresses the expression of Cyclin D1 via directly targeting 3′-UTR of Cyclin D1, inhibiting the proliferation, invasion, and metastasis of gastric cancer cell in vitro and in vivo." (PMID 24995320, 2014).
gastric cancer (continued). "Transfection of si-CCND1 and si-Ets1 resulted in decreased expression of cyclin D1, pRB, Ets1 and MMP-9 in gastric cancer cells, respectively, when compared to those transfected with scramble siRNA (si-Scb)." (PMID 23383271, 2013). "Downregulation of cell cycle proteins, including cyclin D1, CDK4 and CDK6, was also observed in metformin-treated gastric cancer cells." (PMID 24351837, 2013). "In summary, we have demonstrated, for the first time, that miR-9 represses the expression of cyclin D1 and Ets1 through directly targeting their 3′-UTR, thus inhibiting the proliferation, invasion and metastasis of gastric cancer cells." (PMID 23383271, 2013). "All 150 histological specimens of gastric carcinoma were immunohistochemically stained for HER2 and cyclin D1 immunoreactivity." (PMID 23420289, 2013). "While cyclin D1 and CDK4 are well known biomarker of cell proliferation, uPAR and PPARδ have been reported to play role in the migration and invasion of gastric cancer cells." (PMID 22710759, 2012). "In this regard, the CDK1 inhibitor p21 was activated, while cyclin D1 inactivated, after overexpression of ZIC1 in gastric cancer cells." (PMID 22799764, 2012). "The predicted RB-negative frequencies determined by the cut-off value of log10 (CCND1/CDKN2A) of 0.404 were 100% (7/7), 22% (2/9), 100% (5/5), and 5% (1/20) in cervical, endometrial, small cell lung, and gastric cancers, respectively." (PMID 21447152, 2011). "Cervical cancer and SCLC, which are known to be the tumor types with a higher frequency of dysfunctional RB1, showed lower CCND1/CDKN2A ratios compared with endometrial and gastric cancers." (PMID 21447152, 2011). "Cyclin D1 regulates cell cycle progression, explaining in part how CTGF influences the growth of gastric cancer cells." (PMID 21955589, 2011). "By means of FISH (Fluorescence in situ Hybridization), we analyzed the CCND1 and HER-2/neu gene positions within the CTs and their relationship with gene amplification and protein over-expression in esophageal and gastric cancers." (PMID 21637674, 2009). "Supporting findings from aggressive gastric cancer clinical samples with elevated SHCBP1, knockdown of SHCBP1 in gastric cancer cells suppresses the expression of CDK1, CDK4, and cyclin D1, consistent with a block at the G1/S phase transition and reduced cell proliferation." (PMID 41009347, 2025). "Although we demonstrated that CBX4 activates β-catenin signaling and its transcriptional activity, we did not identify or validate the specific downstream target genes (e.g., c-MYC, CCND1, AXIN2) responsible for mediating the oncogenic effects of CBX4 in gastric cancer." (PMID 41502529, 2025). "In this study, the potential target of HL-RG in the treatment of gastric cancer was studied Through PPI network analysis and molecular pairing, TGFB1, CCND1, MMP9, ERBB2, CAT, and PPARα may be the core targets of HL-RG in the treatment of RCC." (PMID 41305721, 2025). "In summary, the NCAPD3 protein may target CCND1 or ESR1 to downregulate downstream factors such as CDK6 and IRSI to inhibit gastric cancer cell proliferation." (PMID 38711992, 2024). "In gastric cancer, DDX21 has been shown to drive cancer cell proliferation, primarily through the activation of the cyclin D1 and CDK2 signaling pathways, suggesting that DDX21 could serve as a therapeutic target for gastric cancer." (PMID 39769343, 2024).